TPPP (tubulin polymerization promoting protein)
Description:
Regulator of microtubule dynamics that plays a key role in myelination by promoting elongation of the myelin sheath. Acts as a microtubule nucleation factor in oligodendrocytes: specifically localizes to the postsynaptic Golgi apparatus region, also named Golgi outpost, and promotes microtubule nucleation, an important step for elongation of the myelin sheath. Required for both uniform polarized growth of distal microtubules as well as directing the branching of proximal processes. Shows magnesium-dependent GTPase activity; the role of the GTPase activity is unclear. In addition to microtubule nucleation activity, also involved in microtubule bundling and stabilization of existing microtubules, thereby maintaining the integrity of the microtubule network. Regulates microtubule dynamics by promoting tubulin acetylation: acts by inhibiting the tubulin deacetylase activity of HDAC6. Also regulates cell migration: phosphorylation by ROCK1 inhibits interaction with HDAC6, resulting in decreased acetylation of tubulin and increased cell motility. Plays a role in cell proliferation by regulating the G1/S-phase transition. Involved in astral microtubule organization and mitotic spindle orientation during early stage of mitosis; this process is regulated by phosphorylation by LIMK2.
Synonyms: TPPP1; p25alpha; p25; TPPP/p25; p24
Tractability: PROTAC: its protein half-life has been measured.
Gene: Protein-coding gene on chromosome 5 (659,862 to 693,997, reverse strand). Ensembl gene ENSG00000171368.
Subcellular location: Golgi outpost; Cytoplasm, cytoskeleton, microtubule organizing center; Cytoplasm, cytoskeleton; Nucleus; Cytoplasm, cytoskeleton, spindle
Subcellular location (Human Protein Atlas): Cytosol; Mitochondria
Gene Ontology:
Molecular function: GTPase activity; magnesium ion binding; protein binding; protein homodimerization activity; tubulin binding; microtubule binding
Biological process: astral microtubule organization; microtubule bundle formation; microtubule nucleation by microtubule organizing center; microtubule polymerization; negative regulation of tubulin deacetylation; positive regulation of protein polymerization; regulation of microtubule cytoskeleton organization; myelin assembly; oligodendrocyte development; oligodendrocyte differentiation; positive regulation of myelination; positive regulation of protein-containing complex assembly
Cellular component: cytoplasm; cytosol; microtubule; microtubule bundle; mitotic spindle; nucleus; perinuclear region of cytoplasm; postsynaptic Golgi apparatus; cytoskeleton; microtubule organizing center; spindle
Genetic constraint (gnomAD): Loss-of-function variants: 6 observed, 15.68 expected, observed/expected ratio (o/e) 0.38, 90% interval 0.21 to 0.75. The upper end of that interval is the gene's LOEUF score, 0.75, which puts it in group 3 of 6, group 1 being the genes least tolerant of losing a copy. Missense variants: 269 observed, 305.15 expected, observed/expected ratio (o/e) 0.88, 90% interval 0.8 to 0.98. Synonymous variants: 146 observed, 129.56 expected, observed/expected ratio (o/e) 1.13, 90% interval 0.98 to 1.29.
Homologues: Orthologues: macaque TPPP (99% identical), chimpanzee TPPP (99% identical), pig TPPP (94% identical), rat Tppp (92% identical), guinea pig TPPP (92% identical), mouse Tppp (92% identical), rabbit TPPP (51% identical), zebrafish TPPP (40% identical), Drosophila melanogaster ringer (35% identical), Caenorhabditis elegans tppp-1 (32% identical). Paralogues in human: TPPP3 (52% identical), TPPP2 (45% identical).
Diseases named in the same sentence as TPPP in open-access papers:
TPPP is named in the same sentence as 44 diseases in open-access papers, as found by Europe PMC text mining. Sharing a sentence is not in itself a finding about the gene and the disease. The quoted sentences say what the papers report.
Parkinson disease (15 papers, 2015 to 2025). A progressive degenerative disorder of the central nervous system characterized by loss of dopamine producing neurons in the substantia nigra and the presence of Lewy bodies in the substantia nigra and locus coeruleus. "In this article, we highlight the role of TPPP in the pathophysiology of Parkinsonism, its potential as a therapeutic target and biomarker, and possible strategies to target the TPPP and SYN hallmark proteins." (PMID 38391951, 2024). "In the normal brain, SYN and TPPP are expressed endogenously in neurons and oligodendrocytes, respectively, whilst, at an early stage of Parkinsonism, soluble hetero-associations of these proteins are found in both cell types." (PMID 38391951, 2024). "Pathologically, TPPP aggregates are associated with Parkinson’s disease and multiple system atrophy, and reversing TPPP aggregation has been proposed as a therapeutic strategy." (PMID 38992434, 2024). "All these issues reveal the anti-mitotic and α-synuclein aggregation-promoting potency of TPPP/p25, consistent with the finding that Parkinson’s disease patients have reduced risk for certain cancers." (PMID 32033023, 2020). "Impairment of autophagosome-lysosome fusion promotes tubulin polymerization-promoting protein (TPPP/p25α) to secrete α-synuclein, the hallmark protein in Parkinson’s disease, in an unconventional manner." (PMID 33363205, 2020). "The precise mechanism by which TPPP/p25 contributes to toxicity in Parkinson’s disease is unknown, however, it is thought that a loss of native function and/or a gain of toxic function are implicated." (PMID 26289831, 2015). "In Parkinson’s, for example, aberrant microtubule structures such as perinuclear cages are formed, mediated by tubulin polymerisation-promoting protein/p25 (TPPP/p25)." (PMID 37943759, 2023). "They include alpha-synuclein (SYN) and Tubulin Polymerization Promoting Protein (TPPP/p25) in Parkinson’s disease (PD), as well as tau and beta-amyloid in Alzheimer’s disease (AD)." (PMID 35163473, 2022). "Parkinson’s disease is characterized by locomotion deficits, dopaminergic neuronal loss and alpha-synuclein (SYN) aggregates; the Tubulin Polymerization Promoting Protein (TPPP/p25 or TPPP1) is also implicated in these processes." (PMID 36230985, 2022). "TPPP plays an important role in pathologicalconditions through the co-enrichment and co-localization of TPPP and α-synucleinin human brain inclusions, such as in Parkinson’s disease (Oláh and Ovádi, 2014)." (PMID 30985858, 2019). "The role of TPPP in Parkinsonism is often neglected in research, which we here attempt to remedy." (PMID 38391951, 2024). "A TPPP-knockout rodent model provided useful insights into the physiological function of TPPP but, from the point of view of Parkinsonism, a TPPP-overexpressing rodent model may contribute to a better understanding of the underlying pathological processes." (PMID 38391951, 2024). "The first TPPP-like protein, TPPP/p25 or TPPP1, was identified in mammalian brain and its physiological significance is connected to the nervous system as well as having a role in neurodegenerative disorders, as Parkinson’s disease and multiple system atrophy." (PMID 37375031, 2023). "An important aspect of Parkinsonism is that the partner proteins in the pathological assembly are expressed in distinct cell types in normal brain: SYN in neurons and TPPP in OLGs, respectively." (PMID 38391951, 2024). "This is in line with other studies, where TPPP and SYN impaired the autophagy flux in different cellular models of Parkinsonism." (PMID 38391951, 2024). "The hypothesis may therefore even prove helpful in understanding and treating diseases like Parkinson’s disease and multiple system atrophy in which the interactions between SYN and TPPP are implicated." (PMID 37433867, 2023).
Parkinson disease (continued). "One of the limitations of Parkinsonism research is the neglect of the key role of TPPP; this neglect may be due to the present lack of knowledge of the molecular mechanism of cell-to-cell transmission of SYN (neuron to OLG) and TPPP (OLG to neuron)." (PMID 38391951, 2024).
multiple system atrophy (12 papers, 2009 to 2025). Multiple system atrophy (MSA) is a neurodegenerative disorder characterized by autonomic failure (cardiovascular and/or urinary), parkinsonism, cerebellar impairment and corticospinal signs with a median survival of 6-9 years. "The last example emphasizes the role of the tubulin polymerization promoting protein (TPPP)/p25 in regulating α-synuclein aggregation in multiple system atrophy (MSA)." (PMID 25784874, 2015). "In multiple system atrophy (MSA), TPPP is suggested to relocate from the myelin sheath to the oligodendroglial cell body, before the formation of glial cytoplasmic inclusions (GCIs), the pathologic hallmark of MSA." (PMID 25208467, 2014). "Under pathological conditions, TPPP/p25 is enriched in glial and neuronal inclusions in synucleinopathies as Parkinson's disease and multiple system atrophy." (PMID 23166627, 2012). "Multiple system atrophy (MSA) is characterized by the presence of distinctive glial cytoplasmic inclusions (GCIs) within oligodendrocytes that contain the neuronal protein alpha-synuclein (aSyn) and the oligodendroglia-specific phosphoprotein TPPP/p25α." (PMID 31011860, 2019).
synucleinopathies (10 papers, 2008 to 2025). "Therefore, TPPP—like SYN—is considered a hallmark of synucleinopathies." (PMID 38391951, 2024). "The occurrence of SYN and TPPP/p25 together are hallmarks of synucleinopathies; these ‘partner proteins’ are co-enriched and co-localized in inclusion bodies in both neurons and oligodendrocytes (OLGs)." (PMID 35163473, 2022). "Here, we used the nerve growth factor–differentiated catecholaminergic PC12 neuronal cell line, which was conferred α-synucleinopathy by inducible expression of αSyn and tubulin polymerization-promoting protein p25α." (PMID 36162505, 2022). "It is generally overexpressed in oligodendroglial cells (OLGs) in the normal brain, but during synucleinopathies such as PD and multiple system atrophy, colocalization and abundant coexpression of α-syn and TPPP/p25 are observed in Lewy bodies and cytoplasmic glial cells." (PMID 37150812, 2023).
depression (8 papers, 2017 to 2023). "Changes in the expression of TPPP are associated with thephenotypes of depression and anxiety following early life stress in humans." (PMID 30985858, 2019). "Results showed that methylation in three genes were considered significant predictors of depression, including Tubulin Polymerization Promoting Protein (TPPP), DNA-Binding Protein Inhibitor-3 (ID3), and Glutamate N-Methyl-d-Aspartic Acid Receptor (GRIN1)." (PMID 30634536, 2019). "In traumatized children, increased methylation in three genes (NMDA glutamate receptor, GRIN1; inhibitor of DNA binding 3, ID3; and tubulin polymerization promoting protein, TPPP) was associated with reduced rates of depression." (PMID 30781888, 2019). "Behavioral differences in the EPM and FST tests showed that these genes, ID3, GRIN1, and TPPP, could predict anxiety and depression." (PMID 28785583, 2017). "In the epigenome study of children, methylation at CpG sites in DNA-binding protein inhibitor ID-3 (ID3), tubulin polymerization promoting protein (TPPP), and Grin1 were inversely related to depression severity in maltreated children." (PMID 35865627, 2022). "Three genes emerged as predictors of depression in combination with ELA: DNA-Binding Protein Inhibitor ID–3 (ID3); and Tubulin Polymerization Promoting Protein (TPPP); and the neurotransmitter gene glutamate receptor, ionotropic N-methyl-D-aspartate 1 (GRIN1)." (PMID 30984237, 2019). "Methylation in four genes developed as predictors of depression: ID3, NMDA, GRIN1, and TPPP." (PMID 30081481, 2018).
multiple sclerosis (4 papers, 2009 to 2025). A progressive autoimmune disorder affecting the central nervous system resulting in demyelination. "In multiple sclerosis (MS), demyelinated lesions show loss of TPPP-positive oligodendroglial cells, whereas re-myelinating areas show TPPP-upregulation in the oligodendroglial cytoplasm, subsequently followed by TPPP expression in the myelin sheath." (PMID 25208467, 2014). "Intriguingly, altered TPPP protein levels have been observed in a number of neurodegenerative disorders, including multiple sclerosis and Parkinson’s disease." (PMID 32296040, 2020). "In GTEx brain samples, high TPPP expression is accompanied by low levels of linc00899, and in multiple sclerosis patients TPPP and linc00899 expression were negatively correlated." (PMID 32296040, 2020).
brain tumor (3 papers, 2008 to 2024). "This inhibition of mitosis would be consistent with the loss of TPPP allowing the proliferation of cancer cells and consistent with the very low level of TPPP reported in a brain tumor (oligodendroglioma)." (PMID 38391951, 2024). "None of the brain tumours showed unequivocal immunopositivity for TPPP/p25." (PMID 18644768, 2008). "Because undifferentiated mitotic precursors do not normally express TPPP/p25, we examined whether TPPP/p25 was expressed in neoplastic cells found in different brain tumours, including oligodendrogliomas." (PMID 18644768, 2008). "However, in the case of oligodendroglioma, a brain tumor, practically no TPPP/p25-positive cells could be detected in the brain tissue of the patients." (PMID 32033023, 2020).
pancreatic cancer (3 papers, 2019 to 2020). "Immunohistochemistry revealed that TPPP was expressed at low levels in pancreatic cancer tissues, and was associated with blood vessel invasion." (PMID 31631174, 2019). "ChIP-sequencing studies showed that YY1 directly binds to the promoter region of TPPP/p25 in the case of pancreatic cancer." (PMID 32033023, 2020). "Our observation that the overexpression of TPPP promoted the migration and invasion of pancreatic cancer cells prompted us to investigate its role in vivo." (PMID 31631174, 2019). "TPPP promotes the migration, invasion and angiogenesis of pancreatic cancer through the p38/MAPK and PI3K/AKT signalling pathways." (PMID 31631174, 2019). "The expression of TPPP in pancreatic cancer was detected by western blotting and immunohistochemistry." (PMID 31631174, 2019). "The results of the Transwell assays showed that TPPP overexpression promoted the migration and invasion of pancreatic cancer cells." (PMID 31631174, 2019). "We performed immunohistochemistry to evaluate the expression of TPPP between pancreatic cancer tissues and their adjacent tissues." (PMID 31631174, 2019). "In this study, we found that TPPP is underexpressed in pancreatic cancer tissues closely related to blood vessel invasion." (PMID 31631174, 2019). "Functional experiments have shown that TPPP overexpression promotes the migration and invasion of pancreatic cancer cells, but this mechanism requires further exploration." (PMID 31631174, 2019). "In vivo experiments revealed that YY1 could inhibit the migration and invasion of pancreatic cancer cells by downregulating the expression of TPPP/p25 via p38/MAPK and PI3K/AKT pathways with undefined mechanism." (PMID 32033023, 2020). "Finally, we found that the upregulation of TPPP also restored the inhibitory effect of YY1 overexpression on pancreatic cancer angiogenesis." (PMID 31631174, 2019). "Our study demonstrates that TPPP may act as a promoter and may serve as a novel target for the treatment of pancreatic cancer." (PMID 31631174, 2019). "Taken together, MMP3 and MMP7 might be involved in the migration and invasion of pancreatic cancer induced by YY1 targeting TPPP." (PMID 31631174, 2019). "In addition, TPPP promoted the migration, invasion and angiogenesis of pancreatic cancer cells, and was regulated by the transcription factor YY1." (PMID 31631174, 2019). "In addition, we also found that the high expression of TPPP promotes the invasion, migration and angiogenesis of pancreatic cancer cells." (PMID 31631174, 2019). "The results from vivo experiments have showed that TPPP could enhance the migration and invasion of pancreatic cancer." (PMID 31631174, 2019). "Further experiments showed that YY1 could inhibit the migration, invasion and angiogenesis of pancreatic cancer cells by downregulating TPPP via p38/MAPK and PI3K/AKT pathways." (PMID 31631174, 2019). "In conclusion, our study revealed the low expression level of TPPP in pancreatic cancer cells." (PMID 31631174, 2019). "The ability of TPPP to promote angiogenesis in pancreatic cancer cells may be related to VEGF." (PMID 31631174, 2019). "This evidence suggests that TPPP might be a new target for treating pancreatic cancer." (PMID 31631174, 2019). "To investigate the effects of TPPP on pancreatic cancer cell function, we used viruses to transfect BxPC-3 and PANC-1 cells to obtain stable cell lines overexpressing TPPP." (PMID 31631174, 2019). "In our research, we delved into the role of TPPP induced by YY1 in the development and progression of pancreatic cancer." (PMID 31631174, 2019). "Cellular Transwell assays and wound-healing assays showed that the upregulation of TPPP restored the inhibitory effect of YY1 overexpression on the invasion and migration of pancreatic cancer cells." (PMID 31631174, 2019).
pancreatic cancer (continued). "It has been reported that tubulin polymerisation-promoting protein (TPPP) plays an indispensable role in a variety of tumours, but its expression and role in pancreatic cancer have not yet been elucidated." (PMID 31631174, 2019). "Therefore, EMT may not be involved in the TPPP-induced migration and invasion of pancreatic cancer cells." (PMID 31631174, 2019).
chronic kidney disease (2 papers, 2022 to 2025). Impairment of the renal function secondary to chronic kidney damage persisting for three or more months. "Five variants associated also with chronic kidney disease progression mapped to genes with functional in-silico evidence (UMOD, SPATA7, GALNTL5, TPPP)." (PMID 35716955, 2022).
cystic fibrosis (2 papers, 2021 to 2025). Autosomal recessive disorder caused by pathogenic variants in the CFTR gene (cystic fibrosis transmembrane conductance regulator), which encodes a chloride and bicarbonate channel expressed in epithelial cells, and follow the diagnosis criteria. "We have demonstrated a role for microtubule dysregulation in several phenotypes in cystic fibrosis, phenotypes that can be mimicked in WT cells by knock-down of TPPP expression and reversed by inhibition of HDAC6." (PMID 34046074, 2021).
Lewy body dementia (2 papers, 2014 to 2022). A progressive form of dementia characterized by the presence of protein deposits called Lewy bodies in the midbrain and cerebral cortex, and loss of cholinergic and dopaminergic neurons. "Tubulin-polymerization promoting protein (TPPP/p25α) is also found within inclusions of PD and Lewy body disease neurons." (PMID 36162505, 2022).
lung carcinoma (2 papers, 2019 to 2020). "Genes at 5p15.33 with potential candidate importance, including TPPP/p25, have been identified; e.g., the amplification of this region marks a major susceptibility locus in lung cancer, and a series of genes in this region may contribute to early stage lung tumorigenesis." (PMID 32033023, 2020). "There is only one study concerning TPPP/p25, which shows lower mRNA expression in 167 lung cancer tissues that was interpreted as: “The role of TPPP may be complicated, and additional studies are warranted to clarify the underlying mechanisms”." (PMID 32033023, 2020).
oligodendroglioma (2 papers, 2014 to 2024). A well-differentiated (WHO grade II), diffusely infiltrating neuroglial tumor, typically located in the cerebral hemispheres. "We investigated the redistribution of TPPP in amyotrophic lateral sclerosis (ALS), MS, and oligodendroglioma, and found that it was specific to MSA." (PMID 25208467, 2014). "To confirm that the relocalization of TPPP is specific to MSA, we performed immunohistochemistry for TPPP in the brains of patients with ALS, oligodendroglioma, and MS." (PMID 25208467, 2014). "In the brain tissue affected with oligodendroglioma, there was a lack of TPPP immunoreactivity, consistent with a previous report." (PMID 25208467, 2014).